STAT3 (signal transducer and activator of transcription 3)
Diseases named in the same sentence as STAT3 in open-access papers (continued):
Sharing a sentence is not in itself a finding about the gene and the disease.
hepatocellular carcinoma (continued). "Moreover, DLX6-AS1 interacts with miR-424-5p via the STAT3 signaling pathway, promoting invasion in WEE1-dependent hepatocellular cancer." (PMID 37245177, 2023). "Moreover, STAT3 silencing reduced the expression of angiogenesis-related genes such as VEGF, MMP-9, and TGF-β in hepatocellular carcinoma cells." (PMID 38067351, 2023). "Interleukin-6 released from α-SMA+ CAFs induces the expression of programmed cell death-ligand 1 (PD-L1) through activation of a signal transducer and activator of transcription 3 (STAT3) in neutrophils and thereby promotes immunosuppression in the TME of hepatocellular carcinoma." (PMID 37174001, 2023). "According to a recent study, GSBXD (Gansui-Banxia Decoction extraction) exhibited anti-tumor immune activity by blocking AKT/STAT3/ERK signaling pathway, limiting IL-1β and IFN-γ level, and decreasing the accumulation and growth of MDSCs in hepatoma-bearing mice." (PMID 37217620, 2023). "Moreover, STAT3 ASO application inhibited angiogenesis, reduced tumor metastasis, and extended the survival of hepatocellular carcinoma-bearing mice compared with the control groups." (PMID 38067351, 2023). "By activating STAT3, TAM-derived IL-6 promotes hepatocellular carcinoma (HCC) development." (PMID 36679900, 2022). "EGCG also inhibited the growth of the human hepatoma cell line HepG2 by inhibiting the phosphorylation of insulin-like growth factor-1 receptor (IGF-1R) and reducing the activation of its signaling molecules, such as ERK, STAT-3, Akt and GSK-3β." (PMID 35873545, 2022). "For example, circLRIG3 preferentially located in the nucleus and interacts with both EZH2 and STAT3 in hepatocellular carcinoma to form a circRNA-protein complex, facilitating EZH2-induced activation of STAT3 signaling and promoted HCC cell proliferation and metastasis." (PMID 35986300, 2022). "G6PD levels have been shown to be elevated in many cancers, and it has been shown that G6PD induces epithelial-mesenchymal transition by activating the signal transducer and activator of transcription 3 pathway, thereby promoting HCC migration and hepatoma cell invasion." (PMID 36347033, 2022). "Furthermore, in hepatocellular carcinoma, ACh acting on androgen receptor endorses SNU-449 cell invasion and migration via activation of signal transducer and activator of transcription 3 (STAT3) and AKT signaling pathways." (PMID 36614038, 2022). "Furthermore, this study demonstrates that TPGS-FA/NC suppresses hepatoma cell proliferation and hepatic CSCs, as well as the AQP3/STAT3/CD133 axis and Nek2 expression in offering possible multiple mechanisms for its antitumor activity." (PMID 35820920, 2022). "Similarly, Quercetin inhibits hepatocellular carcinoma progression by down-regulation of the activation of JAK2 and STAT3." (PMID 36195876, 2022). "In human hepatoma cells, GSH inhibited the egg product-induced activation of ERK, c-JUN, and STAT3." (PMID 36590323, 2022). "Similarly, IHC was performed on HCC samples from 80 clinical patients, resulting in a malignant degree of hepatocellular carcinoma, lower CYB5A and LC3 expression levels, and higher STOML2 and p-STAT3 expression levels." (PMID 35851063, 2022). "Because chronic FGF19 overexpression was shown to induce hepatocellular carcinoma in mice by activating STAT3 signaling, a nontumorigenic FGF19 analogue (NGM282, also known as M70 and aldafermin) that does not activate STAT3 was developed." (PMID 35415765, 2022). "The oxidative hepatic environment in obesity induces PTPN2 inactivation and the resultant enhanced STAT1 and STAT3 signaling, which promotes T cell recruitment and ensures non-alcoholic steatohepatitis and fibrosis, as well as hepatocellular carcinoma." (PMID 36077422, 2022).
hepatocellular carcinoma (continued). "In hepatocellular carcinoma, eEF2K promotes angiogenesis through PI3K/Akt and STAT3 signaling." (PMID 33673713, 2021). "In human hepatocellular carcinoma, PDIA3 downregulation inhibits cell proliferation and, through STAT3 signaling, induces apoptosis in agreement with the observation that PDIA3 knockdown reduces phosphorylated STAT3 and downstream STAT3-related protein levels." (PMID 34829762, 2021). "In hepatocellular carcinoma, DDR1 activates STAT3 which, in turn, increases DDR1 mRNA expression." (PMID 33917302, 2021). "Interestingly, increased p-STAT3 expression in the CD4+ and CD8+ T cells in peripheral blood of patients with hepatocellular carcinoma can lead to aberrant immunological surveillance, thus promoting the development of hepatocellular carcinoma." (PMID 33435880, 2021). "Inhibition of ANT2 may inhibit STAT3 activity by restoring SOCS1 expression and by downregulate miR-21, thereby exerting anticancer effects in human hepatocellular carcinoma cells." (PMID 34539732, 2021). "In this study, we demonstrate that the mitochondrial OXPHOS defect enhances NFE2L1 transcription via reactive oxygen species (ROS)-mediated STAT3 activation, and the upregulation of NFE2L1 increased hepatoma cell invasiveness by inducing syntaxin 12 (STX12) expression." (PMID 32942643, 2020). "To explore whether OF anti‐HCC effect is through the ASGR/STAT3/HNF4A pathway, we knockdown the ASGR and HNF4A in Hep3B hepatoma cells, and performed the functional analysis for cell viability assay." (PMID 33377648, 2020). "IL-6 induces human HO-1 gene expression via the JAK/STAT3 pathway in HepG2 cells; however, there is a negative autocrine between expressions of HO-1 and IL-6 in human hepatoma cells." (PMID 32204510, 2020). "In addition, the LINC01287/miR-298/STAT3 feedback loop modulates the growth and EMT phenotype of hepatocellular carcinoma (HCC) cells." (PMID 33614632, 2020). "In hepatocellular carcinoma cells, NCTD reversed IL-6-induced epithelial-mesenchymal transition process and inhibited STAT3 phosphorylation like JSI-124, a selective inhibitor of STAT3." (PMID 31315217, 2019). "However, first we needed to clarify the potential signaling pathways through which the miR‐125b‐5p/STAT3 axis regulated the EMT and CSC in hepatoma cells." (PMID 31065520, 2019). "Our results suggest that RORα activators could provide a good strategy for the development of effective therapeutics for liver diseases mediated by the IL-6Rα–STAT3 axis, such as hepatic injury with APR and hepatocellular carcinoma." (PMID 31409825, 2019). "G6PD could activate the STAT3 pathway to induce the EMT process and further promote the migration and invasion of hepatocellular carcinoma cells." (PMID 29954422, 2018). "For example, a direct cross talk between Smad3 and STAT3 is bridged by p300 in hepatoma cells, a synergistic action of LIF-induced-Smad1 and BMP2-induced-STAT3 is bridged by p300 in neural cells, and Smad2/3 and STAT3 cooperatively interact in Th17 cell differentiation." (PMID 29963056, 2018). "Besides, since pimozide is a well-known antagonist of serotonin 5-hydroxytryptamine receptor 7 (5HT7), which was overexpressed in human hepatocellular cancer (Data not shown,), whether 5HT7 expression is associated with STAT3 activation in HCC cells is required to investigated in future." (PMID 26061710, 2017). "Consistently, CRNDE promoted hepatic carcinoma cell proliferation, invasion and migration by sponging miR-384, and CRNDE also promoted malignant progression of glioma by attenuating miR-384/PIWIL4/STAT3 axis." (PMID 29299168, 2017). "IL-6/STAT3-mediated CSC marker, CD133 up-regulation contributes to promotion of liver carcinoma." (PMID 28507278, 2017). "As a result, M70 fails to activate the proliferative factor Stat3 and does not promote hepatocellular carcinoma formation in mice, while retaining the ability to maintain BA homeostasis and even to ameliorate BDL- and ANIT-induced cholestasis in mice." (PMID 28178326, 2017).
hepatocellular carcinoma (continued). "To determine whether blocking STAT3 could increase the immunogenicity of HCC and apply a tumor vaccine against HCC, we prepared the tumor vaccine using two murine hepatoma cell lines H22 and Hepa1–6." (PMID 29115974, 2017). "The link between HIF-1α and STAT3 occurs at different levels, and is further supported by studies showing that HIF-1α facilitates the binding of STAT3 to the haptoglobin promoter in HepG2 human hepatoma cells." (PMID 26501341, 2015). "A recent study showed that sorafenib resistance in hepatocellular carcinoma cells may at least partly be related to p38α (MAPK14)-dependent MEK-ERK activation, but other downstream proteins, such as STAT3, also seem to be important." (PMID 25665527, 2015). "Moreover, inhibition of constitutive STAT3 signaling by the JAK2 inhibitor AG490 suppressed the growth and invasion of human hepatocellular carcinoma cells, and also induced apoptosis in multiple myeloma cells." (PMID 26417930, 2015). "STATIP1 overexpression blocked STAT3 activation in the human hepatocellular carcinoma cell line HepG2, suggesting a negative role for STATIP1 in STAT3 regulation." (PMID 25417721, 2014). "For example, upon treatment of hepatoma cells and primary human macrophages with IL-6-type cytokines (e.g. IL-6 or OncostatinM) STAT1 phosphorylation can be observed but most of the phosphorylated STAT1 is rather trapped in STAT1/STAT3 heterodimeric complexes." (PMID 20719000, 2010). "Furthermore, inhibition of constitutive STAT3 signaling by the JAK2 inhibitor, AG490 suppressed the growth, and decreased the invasion of human hepatocellular carcinoma cells, and also induced apoptosis in multiple myeloma cells." (PMID 20712901, 2010). "Our present data fits to our previous observation that IL-27 does not regulate the STAT3-dependent acute-phase proteins γ-fibrinogen and hepcidin in hepatocytes and hepatoma cells." (PMID 20719000, 2010). "This suggests that adiponectin may affect the pathogenesis of prostate and hepatocellular carcinomas, which express AdipoR1 and R2 receptors, by acting on tumour cells directly through modulation of JNK and STAT3." (PMID 16570048, 2006). "Similarly, in hepatocellular carcinoma (HCC), ECM stiffness (12 kPa) compared with soft ECM (1 kPa) activates the protein kinase B (PKB)/AKT, and signal transducer and activator of transcription 3 (STAT3) pathways, promoting tumor cell proliferation." (PMID 40686923, 2025). "Dasatinib, an indirect STAT3 inhibitor, significantly facilitated anti-CTLA-4 immunotherapy in head and neck squamous cell carcinoma, while the combined blockade of IL-6 and PD-L1 remarkably inhibited the growth of pancreatic ductal adenocarcinoma and hepatocellular carcinoma." (PMID 40963562, 2025). "In addition, COX-2 gene expression is downregulated by STAT3 phosphorylation in hepatocellular carcinoma cells, demonstrating that COX-2 gene expression is not necessarily upregulated by JAK–STAT signaling activation." (PMID 40043951, 2025). "In various cancers, including malignant glioma, gastric cancer, salivary adenoid cystic carcinoma, and hepatocellular carcinoma (HCC), B7-H3 promotes epithelial-to-mesenchymal transition (EMT) via the activation of the JAK2/STAT3/Slug signaling pathway." (PMID 40214484, 2025). "In hepatocellular carcinoma, M1 macrophages secreted significantly higher levels of IL-35 than M2 macrophages, which promoted the EMT process by activating STAT3 in cancer cells, and cancer cell-tumor microenvironment interactions could promote tumor growth and metastasis." (PMID 40259042, 2025). "Similarly, in hepatocellular carcinoma (HCC), toosendanin (TSN), a novel agonist of WWOX, dose-dependently increases WWOX mRNA and protein expression and enhances its interaction with STAT3 and Dvl2, thereby inhibiting both the JAK2/STAT3 and Wnt/β-catenin signaling pathways." (PMID 41228229, 2025).
hepatocellular carcinoma (continued). "In hepatocellular carcinoma (HCC) cells, MUC1 can promote radio resistance by activating the JAK2/STAT3 signaling pathway." (PMID 38164273, 2024). "In hepatocellular carcinoma (HCC), polyphyllin VI hinders STAT3 phosphorylation, suppresses GPX4 expression and triggers ferroptosis in HCC cells, ultimately hindering invasion and metastasis." (PMID 38205151, 2024). "In hepatocellular carcinoma cells (HCC), CA curbed VEGF and vascularization induced by CoCl2, accomplishing this through the stabilization of STAT3/JNK1/HIF-1α." (PMID 39062873, 2024). "The signal transducer and activator of transcription 3 (STAT3) regulates glucose metabolism in hepatocellular carcinoma (HCC) through the HK II mTOR-mediated pathway, contributing to the development of HCC." (PMID 38202657, 2023). "In hepatocellular carcinoma (HCC), PTPN20 may act as an inhibitor for the STAT3 signaling pathway." (PMID 37359510, 2023). "In addition, NLRC3 silencing may play an important role in cancer progression and prognosis of hepatocellular carcinoma via the activation of Janus kinase 2/signal transducers and the transcription 3 (JAK2/STAT3) pathway under interleukin-6 (IL-6) stimulation." (PMID 37964222, 2023). "In addition, STAT3, a transcription factor important for HCC development, promotes hepatocellular carcinoma stem cell expansion and has important functions in tumorigenesis, progression, recurrence, and drug resistance in hepatocellular carcinoma." (PMID 37326750, 2023). "TGF-β1-induced EMT depends on crosstalk with STAT3 signaling in hepatocellular carcinoma (HCC) cells, and positive p-STAT3 and TGF-β1 proteins were co-expressed in the liver tissues of HCC patients." (PMID 38136312, 2023). "In Hepatocellular Carcinoma (HCC), circ_0072088 activates JAK2/STAT3 signaling pathway and enhances the proliferation, migration, and invasion ability of HCC cells." (PMID 38006726, 2023). "It was discovered that CAFs from hepatocellular carcinoma impact T cell development and function, as well as the patient’s overall longevity, by enticing monocytes to the TME by releasing CXCL12 and driving them to transform into MDSCs by activating STAT3 through IL-6." (PMID 37007004, 2023). "STAT3 functions as a positive regulator in TGFBeta1-induced epithelium-mesenchymal transition (EMT) and metastases in hepatocellular carcinoma (HCC)." (PMID 35406724, 2022). "Dang Yang ‘s team found that H2S can down-regulate IDO1 expression by blocking NF-κB and STAT3 pathways and inhibit IDO1 activity through H2S/NO cross-talk, which has an immunotherapeutic effect on H22 hepatocellular carcinoma (HCC) tumor-bearing mice." (PMID 36558139, 2022). "DLGAP1-AS1 sequestered miR-486-5p to promote cell proliferation of hepatocellular cancer, and DLGAP1-AS1 urged the occurrence of liver cancer and epithelial-mesenchymal transition through the feedback loop of the miR-26a/b-5p/IL-6/JAK2/STAT3 and Wnt/β-catenin pathways." (PMID 35341001, 2022). "Moreover, IL25 could promote proliferation and sustain self-renewal of NANOG positive hepatocellular carcinoma by activating NF-κB and JAK/Stat3 pathways." (PMID 35359953, 2022). "Similarly, patient-derived hepatocellular carcinoma CAFs were shown to upregulate the expression of PD-L1 on the surface of neutrophils, another prominent component of the TME, through secretion of IL-6 and activation of a STAT3-dependent signalling pathway." (PMID 32967079, 2020). "New findings suggest that IRE1α-XBP1 signaling promotes development of tumors such as hepatocellular carcinoma (HCC) or melanoma via upregulation of IL-6-driven Janus kinase-signal transducer and activator of transcription 3 (JAK-STAT3) signaling pathway." (PMID 31491919, 2019). "Signal transducer and activator of transcription 3 (STAT3) is an oncogene constitutively activated in hepatocellular carcinoma (HCC) cells and HCC cancer stem cells (CSCs)." (PMID 30709346, 2019).
hepatocellular carcinoma (continued). "Like STAT3, experimental evidence implicates STAT5B as a driver of tumorigenesis, as it can drive EMT and increased invasiveness in hepatocellular carcinoma (HCC)." (PMID 31684144, 2019). "Based on their activites at nM range for inhibition of STAT3 dimers, OPB-31121 and OBP-51602 are some of the most promising ones andentered clinical trials in advanced leukemias, myelodysplastic syndromes, multiple myeloma or advanced solid tumors such as hepatocellular carcinoma." (PMID 29921764, 2018). "In hepatocellular carcinoma (HCC), ATF3 cooperates with SPTBN1 and SMAD3 to inhibit STAT3 activity, thereby suppresses HCC development." (PMID 30455690, 2018). "Moreover, WT1-AS could upregulate expression of WT1 to inhibit hepatocellular carcinoma cell proliferation and apoptosis via activating JAK2/STAT3 and MAPK signaling pathway." (PMID 30406146, 2018). "Signal transducer and activator of transcription 3 (STAT3) is involved in hepatitis B virus (HBV) infection and HBV-related hepatocellular carcinoma (HCC)." (PMID 29609539, 2018). "In hepatocellular carcinoma (HCC), lncRNA Nuclear Enriched Abundant Transcript 1 (NEAT1) functioned as competing endogenous lncRNA (ceRNA) to regulate STAT3 by sponging miR-485 for HCC development." (PMID 29654165, 2018). "Signal transducer and activator of transcription 3 (STAT3) and hexokinase 2 (HK2) are involved in hepatocellular carcinoma (HCC)." (PMID 28445971, 2017). "Hepatoma cell lines that were classified as epithelial due to their E-cadherin expression were sensitive to EGFR inhibitors, whereas hepatoma cell lines classified as mesenchymal (vimentin-positive) were resistant to EGFR inhibitors and displayed increased Akt and STAT3 phosphorylation." (PMID 26729094, 2015). "Consistently in experiments performed in vitro, B7-H3 was able to stimulate the wound healing, metastasis and invasion of hepatoma cells by targeting epithelial-to-mesenchymal transition (EMT) via JAK2/Stat3/Slug signaling pathway, while no obvious influence on cell growth and apoptosis." (PMID 25908926, 2015). "In a hepatocellular carcinoma (HCC) model, it was shown that TAM secrete IL-6 activating STAT3 in HCC cells and promoting expansion of cancer stem cells." (PMID 26074923, 2015). "Therefore, we examined whether STAT3 and BNIP3 are involved in the ConA-induced autophagy of hepatoma cells." (PMID 26633714, 2015). "Indeed, treating hepatoma cells with recombinant human MIF (rMIF) directly induced BNIP3 expression but not STAT3 phosphorylation, which were activated by ConA." (PMID 26633714, 2015). "While TGFβ1 mediated activation of STAT3 in skeletal muscles was not reported previously, TGFβ1 activated STAT3 by phosphorylating Tyr705 has been reported in hepatic cells and a mouse model of hepatocellular carcinoma." (PMID 26380299, 2015). "Therefore, in HepG2 hepatocellular carcinoma cells, PKR positively regulates STAT3 phosphorylation, a process hypothesized to determine the activity of STAT3." (PMID 25360179, 2014). "Therefore, we further investigated, if SERPINA3 upregulation is STAT3-dependent, since SERPINA3 has been shown to be a prototypic acute phase molecule up-regulated upon OSM stimulation in hepatoma cells as also demonstrated in IEC in our microarray experiments." (PMID 24710357, 2014). "Because hepatitis C virus (HCV) core protein (Core), protein kinase R (PKR), and signal transducer and activator of transcription 3 (STAT3) all play relevant roles in the pathogenesis of HCV, persistent infection and hepatocellular carcinoma (HCC) and PKR may interact with HCV Core." (PMID 22312393, 2010). "In hepatoma cells, inhibition of miR-411-5p reversed MIAT knockdown-triggered suppression of STAT3 and PD-L1 expression, and regulation of the autophagy-related gene STAT3 by miR-411-5p may also be involved in the therapy of C. albicans infection with itraconazole and ritonavir." (PMID 40727105, 2025).